PCAT6 (prostate cancer associated transcript 6)
Diseases named in the same sentence as PCAT6 in open-access papers (continued):
Sharing a sentence is not in itself a finding about the gene and the disease.
tumor (continued). "In the current study, we discovered that lncRNA PCAT6, which was aberrantly upregulated in ESCC tumor tissues, significantly promoted cell proliferation and migration in ESCC cell lines Eca-109 and Kyse-30 cells." (PMID 35069911, 2022). "PCAT6 promotes HCC cell proliferation and invasion in vitro, and tumor growth in vivo by attenuating miR-326 and upregulating heterogeneous nuclear ribonucleoprotein A2/B1 (HNRNPA2B1)." (PMID 34885209, 2021). "In summary, this study reveals that m6A‐modified PCAT6 interacts with IGF2BP2 to stabilize IGF1R mRNA, which promotes PCa BM and tumor growth." (PMID 34185427, 2021). "To further assess the effect of PCAT6 on PCa tumor growth in vivo, we subcutaneously injected PCAT6‐knockdown or control PC‐3 cells into BALB/c nude mice and measured tumor activity." (PMID 34185427, 2021). "Overall, METTL3‐mediated m6A modification contributes to the upregulation of PCAT6 in an IGF2BP2‐dependent manner and the PCAT6/IGF2BP2/IGF1R complex further stabilizes IGF1R mRNA to activate downstream pathways, which promotes BM and tumor growth in PCa." (PMID 34185427, 2021). "Firstly, to study the relationship between PCAT6 expression and the development of CCA, relative PCAT6 expression levels were obtained compared with non-tumor tissues (n = 20 pairs)." (PMID 33552977, 2020). "PCAT6 promoted TNBC cell proliferation, migration, invasion, EMT, and angiogenesis, as well as tumor growth and metastasis via upregulation of VEGFR2 through sponging miR-4723-5p and recruiting USP14." (PMID 32908134, 2020). "SNHG3, RMRP, PCAT6, and LSINCT5 expression positively correlated with tumor size and TNM stage, while high expression of MAFG-AS1, SNHG7, and TMPO-AS1 was closely related to histological grade, tumor size, TNM stage, and clinical stage of BCa patients." (PMID 34611133, 2021). "In addition, PCAT6 also upregulates the ZEB1 level by absorbing miR-143-3p in Osa, promoting cell proliferation, migration, invasion, and cell cycle in vitro, and tumor growth in vivo." (PMID 34885209, 2021). "In addition, a significant correlation was observed between PCAT6 overexpression and individual tumor clinicopathological parameters, including TNM stage, gender, and tumor metastasis." (PMID 34247605, 2021). "PCAT6 promoted TNBC tumorigenesis, angiogenesis, tumor growth, and metastasis via the upregulation of VGEFR2, which might shed new insight into TNBC treatment." (PMID 32908134, 2020). "Finally, PCAT6 (p = 0.02) and LANCL1-AS1 (p = 0.01) expression was significantly lower in poorly differentiated tumours when compared to well and moderately differentiated ones." (PMID 32020063, 2020). "Furthermore, PCAT6 enhances IGF1R mRNA stability via the PCAT6/IGF2BP2/IGF1R RNA-protein trimer, thereby upregulating IGF1R expression and promoting PCa bone metastasis and tumor growth." (PMID 38166703, 2024). "In addition, PCAT6 enhances IGF1R mRNA stability via the PCAT6/IGF2BP2/IGF1R RNA–protein trimer, thereby upregulating IGF1R expression and promoting PCa bone metastasis and tumor growth." (PMID 38117350, 2023). "Therefore, we performed RT‐qPCR assays to identify target mRNAs that were regulated by both PCAT6 and IGF2BP2 in these tumor‐related mRNAs and found that IGF1R was the most downregulated mRNA both in PCAT6‐ and IGF2BP2‐knockdown PC‐3 cells compared with control PC‐3 cells." (PMID 34185427, 2021). "Moreover, in NSCLC, PCAT6 transcriptionally impairs large tumor suppressor kinase 2 (LATS2) promoter activity by binding to EZH2, which mediates H3K27 trimethylation and accelerates the cell cycle, promoting cell proliferation, tumor growth and metastasis, and hindering cell apoptosis." (PMID 34885209, 2021). "However, PCAT6 overexpression was not correlated with patient age and tumor differentiation." (PMID 34247605, 2021). "Regarding the correlation between PCAT6 overexpression and TNM stage, a negative correlation was observed between PCAT6 expression and advanced tumor stage (III + IV)." (PMID 34247605, 2021).
infection (2 papers, 2018 to 2021). The state of being infected such as from the introduction of a foreign agent such as serum, vaccine, antigenic substance or organism. "Furthermore, a xenograft mouse model and lentiviral infection of SW620 cells (SW620-LV-PCAT6) revealed that PCAT6 contributes to the tumorigenesis of CRC cells in vivo." (PMID 34327141, 2021). "Mosquitoes that blood-fed on the secondary infected canaries developed infections with Pcat6 as well as another P. cathemerium lineage (Pcat8); none developed PCR detectable P. homopolare infections." (PMID 29845414, 2018). "During this infection period, PCR detected Pcat6, but not P. homopolare in the canary." (PMID 29845414, 2018).
PCAT6 also shares sentences with these, for which no sentence is quoted: liver cancer (3 papers); adenocarcinoma (1); clear cell renal cell carcinoma (1); gastrointestinal stromal tumor (1); laryngeal squamous cell carcinoma (1); ovarian serous cystadenocarcinoma (1); pancreatic cancer (1); pancreatic ductal carcinoma (1); thymoma (1); Urothelial Bladder Carcinoma (1).